ETS2 (ETS proto-oncogene 2, transcription factor)
Diseases named in the same sentence as ETS2 in open-access papers (continued):
Sharing a sentence is not in itself a finding about the gene and the disease.
ETS2 also shares sentences with these, for which no sentence is quoted: asthma (2 papers); Ewing sarcoma (2); ulcerative colitis (2); acne (1); adenocarcinoma (1); aneurysm (1); ankylosing spondylitis (1); Anxiety (1); autoimmune disease (1); basal cell carcinoma (1); bone cancer (1); cervical intraepithelial neoplasia (1); cervical squamous cell carcinoma (1); chordoma (1); chronic myeloid leukaemia (1); colon adenocarcinoma (1); developmental verbal dyspraxia (1); diffuse large B-cell lymphoma (1); digestive system carcinoma (1); endometrial cancer (1); endothelial dysfunction (1); fibrosis (1); hyperplastic polyp (1); hyperprolactinemia (1); infarction (1); insulin-dependent diabetes mellitus (1); leishmaniasis (1); lentivirus infection (1); liver cancer (1); lung adenocarcinoma (1).
A further 14 diseases each share a sentence with ETS2 in 1 paper.